NOTCH1 (notch receptor 1)
Diseases named in the same sentence as NOTCH1 in open-access papers (continued):
Sharing a sentence is not in itself a finding about the gene and the disease.
medulloblastoma (continued). "In medulloblastoma, the most common pediatric brain tumor, the expression of the NOTCH2 receptor is higher than NOTCH1, resulting in the accumulation of the NOTCH2 intracellular domain and its tumor-promoting effect." (PMID 32796631, 2020). "On the other hand, both TWIST1- and BMI1-silenced medulloblastoma cells present similar levels of NICD1 expression as compared with control, suggesting that NOTCH1 is upstream of TWIST1 and BMI1." (PMID 30297829, 2018). "Of note, similarly to NOTCH1, BMI1 and Nestin are weakly expressed in Group 3 medulloblastoma primary tumors from D425 xenografted mice." (PMID 30297829, 2018). "Together, these findings indicate that the NOTCH1-induced TWIST1 activation contributes to the activation of BMI1, therefore inducing Group 3 medulloblastoma metastasis." (PMID 30297829, 2018). "For example, in medulloblastomas, NOTCH2 was shown to promote tumorigenesis, whereas NOTCH1 inhibited tumor growth." (PMID 28968975, 2017). "The Eberhart group previously showed that expression of Notch2 but not Notch1 was upregulated in medulloblastoma compared with normal pediatric cerebella, although they did not discriminate between SHH and the other subgroups." (PMID 33762301, 2021). "Tumor formation was observed in nine of the ten mice injected with NOTCH1+ medulloblastoma cells, as opposed to tumor formation in only one of the 10 mice injected with NOTCH1− higher survival rate medulloblastoma cells." (PMID 30297829, 2018). "We transfected Group 3 medulloblastoma cells (D425 and D283) with two constructs: 1) EF1.GFP.T2A.Luc, for constitutive expression of GFP and luciferase and 2) doxycycline/RFP-inducible short hairpin RNA (shRNA) to NOTCH1, for reducing NOTCH1 expression." (PMID 30297829, 2018). "Finally, medulloblastoma-bearing mice intrathecally treated with anti-NRR1, a NOTCH1 blocking antibody, present lower frequency of spinal metastasis and higher survival rate." (PMID 30297829, 2018). "Since NOTCH1 activity can drive cancer metastasis by modulating the epithelial–mesenchymal transition (EMT), tumor angiogenesis processes and the anoikis resistance of tumor cells, we asked if NOTCH1 activity regulates Group 3 medulloblastoma metastasis." (PMID 30297829, 2018). "Medulloblastoma is characterized by an upregulation of the receptor NOTCH2, but not NOTCH1, and an increase in Hes1 expression correlates with poor prognosis." (PMID 32796631, 2020).
neuroblastoma (21 papers, 2004 to 2025). Neuroblastoma (NB) is the most common solid, extracranial childhood tumor. "The Notch signaling pathway has been shown to inhibit neuroblastoma tumor cell differentiation and Notch1 expression has been shown to be associated with high-risk tumor features and poor prognosis in a cohort of children with neuroblastoma." (PMID 22363512, 2012). "The association of NOTCH1 overexpression with adverse clinical outcome in our series is expanding previous data obtained by means of the immunohistochemical analysis of Notch1 protein in a large series of neuroblastomas." (PMID 36121500, 2022). "The impact of NOTCH1 overexpression in the adverse clinical behavior of neuroblastoma patients in our series is to be further validated in a biological perspective." (PMID 36121500, 2022). "A previous in vitro study is partly in contrast with our findings and shows that Notch1 inhibition prevents neurite formation in neuroblastoma cells." (PMID 36121500, 2022). "In a similar manner, VPA upregulated Notch1 and inhibited growth of cancer cells in vitro and in vivo in a mouse xenograft model in pulmonary carcinoid, gastrointestinal, and neuroblastoma models." (PMID 34068438, 2021). "In particular, neuroblastoma growth inhibition was demonstrated following exogenous expression of the intracellular domain of all three NOTCH proteins (NOTCH1-3)." (PMID 32210188, 2020). "Previous studies have found that VPA increased levels of the full-length NOTCH1 protein and transmembrane protein in neuroblastoma cells, as well as the NOTCH1 full-length protein and the intracellular domain in carcinoid cancer cells." (PMID 28881812, 2017). "Fzd6 positive neuroblastoma cells form neurospheres with high efficiency, are resistant to doxorubicin killing and express high levels of mesenchymal markers such as Twist1 and Notch1." (PMID 22249030, 2011). "Interestingly, in a translational view, the demonstration of NOTCH1 expression in neuroblastoma and its positive correlation with aggressiveness is paralleled by in vitro data on the efficacy of Notch1 inhibition in neuroblastoma cells." (PMID 36121500, 2022). "However, among the possible mechanisms, Notch1 has been shown to actively maintain a stem cell phenotype in neuroblastoma cells that confer highly tumorigenic properties." (PMID 36121500, 2022). "Moreover, the Notch1 inhibitor NSI-1 has recently shown to suppress the viability of SH-SY5Y neuroblastoma cells characterized by a constitutive Notch1 activation." (PMID 36121500, 2022). "Likewise, it has been shown that treatment of neuroblastoma (NB), human gastrointestinal, and pulmonary carcinoid cancer cells with VPA caused an increase in Notch1 activity and inhibition of cancer cell growth in vitro and in vivo in a mouse xenograft model." (PMID 31357442, 2019). "Notch1 intracellular domain is first found in sub-nuclear bodies in SH-SY5Y neuroblastoma." (PMID 25951238, 2015). "Notably 5 microRNAs (miR-200a,b,c and miR-34b,c), including those most downregulated in the tumors, correlated to NOTCH signaling and directly targeted NOTCH1 in in vitro experiments using SH-SY5Y neuroblastoma cells." (PMID 23955600, 2013). "Interestingly, Notch signaling plays a key role in fate selection of neuronal cells and we have previously shown that over expression of a constitutively active form of Notch-1 inhibits induced differentiation of neuroblastoma cells." (PMID 15544702, 2004). "In conclusion, we identify a strong prognostic impact of neuroendocrine-lineage transcriptional profiles in neuroblastoma, and suggest that the evaluation of NOTCH1, INSM1, YAP1, and NEUROD1 might help to further characterize the risk of relapse in neuroblastoma patients." (PMID 36121500, 2022). "Evidence for NOTCH1-independent HES1 expression has been demonstrated in Ewing’s sarcoma, neuroblastoma and endothelial cells through mechanisms that involve JNK signaling or HIF-1-mediated hypoxia signaling, among others." (PMID 41009728, 2025).
neuroblastoma (continued). "RT-qPCR analysis of the three mammalian Notch receptors (Notch 1, Notch 2, and Notch 3) in SH-SY5Y, KELLY and IMR-32 neuroblastoma cell lines." (PMID 28525978, 2017). "It has been reported that, in gastric cancer cells and neuroblastomas, the hypoxic microenvironments induced EMT and concretely in neuroblastoma, it elevated the expression of SC markers such as Notch1." (PMID 29194401, 2017). "Moreover, genes that have previously been established to drive neuroblastoma progression and migration, including DBH, NOTCH1, RET and WNT1, were down regulated in response to TRPM7 knockdown." (PMID 25797249, 2015). "We have previously shown that inhibiting Notch signaling with the soluble Notch1 decoy (N1D) decreased viability (but not tumor weight), disrupted vasculature, disorganized the interaction of endothelial cells with pericytes in neuroblastoma NGP xenografts." (PMID 24066611, 2013). "It is currently not clear whether a link between Pax-5 and Notch1 expression is at hand in neuronal cells, but it is noteworthy that neuroblastoma cells express relatively high levels of Pax-5." (PMID 15544702, 2004).
Adams-Oliver syndrome (20 papers, 2015 to 2026). Adams-Oliver Syndrome (AOS) is a rare disorder characterized by the combination of congenital limb abnormalities and scalp defects, often accompanied by skull ossification defects. "We show that RBPJ variants associated with Adams-Oliver Syndrome act as dominant-negative proteins that reduce Notch1 signaling in the endothelium to cause pathogenesis." (PMID 41055965, 2025). "Human genetic studies previously revealed that Adams Oliver Syndrome (AOS) is associated with autosomal dominant alleles in the NOTCH1, DLL4, and RBPJ genes." (PMID 35951645, 2022). "Despite its involvement in many key developmental systems, variants in the NOTCH1 gene are mainly associated with autosomal dominant aortic valve disorder and Adams-Oliver Syndrome." (PMID 33829027, 2021). "Heterozygous mutations in DLL4 (ligand) and NOTCH1 (receptor) lead to Adams Oliver syndrome with CHD present in about 25% of these patients." (PMID 33585486, 2021). "Variants in RBPJ which interacts with the cleaved NOTCH1 protein to form a transcriptional complex, are also linked to Adams Oliver syndrome." (PMID 33585486, 2021). "Germline mutations in NOTCH1 cause aortic valve disease and have been found to cause Adams-Oliver syndrome." (PMID 31480400, 2019). "For example, a 85-kb de novo deletion spanning the 5′ region of NOTCH1 and causing Adams-Oliver syndrome." (PMID 25741365, 2015). "In addition, NOTCH1-variants are known to cause Adams-Oliver syndrome, a condition mainly characterized by terminal transverse limb defects, aplasia cutis congenita, and various forms of CHD." (PMID 41501857, 2026). "Furthermore, ARHGAP31 and NOTCH1 have both been associated with Adams-Oliver syndrome (OMIM#100300, OMIM#616028), which is associated with severe cardiac malformations such as valvular defects and TOF." (PMID 27760138, 2016). "NOTCH 1 is a member of the Notch signaling pathway and variants in this gene have been reported as causative for left-sided obstructive cardiac lesions (often aortic valve stenosis) and vascular anomalies including aneurism of the ascending aorta and Adams-Oliver syndrome." (PMID 41010011, 2025). "The in-silico findings regarding the critical role of ASP-1987 were aligned to the observation that the substitution in Adams-Oliver syndrome leads to disruption of Notch-1 signalling." (PMID 35585601, 2022). "The phenotypic expansion in our family cohort is intriguing due to the previous association of NOTCH1 and ARHGAP31 with Adams-Oliver syndrome (AOS)." (PMID 27760138, 2016). "None of these adults with NOTCH1 ultra-rare variants had a history of a clinical diagnosis of Adams-Oliver syndrome (AOS5, OMIM: 616028), a rare multi-system developmental syndrome associated with pathogenic NOTCH1 variants and mechanism proposed to involve vascular disruption." (PMID 33110418, 2020). "Notably we did not observe characteristics of Adams-Oliver syndrome in patients with NOTCH1 nonsense mutations but one incidence of aortic valve disease." (PMID 27760138, 2016).
aortic valve disease (20 papers, 2014 to 2025). "For example, NOTCH1 haploinsufficiency can cause human disease such as AOS and aortic valve disease, whereas a Notch1-null (N1-null) allele is well tolerated in heterozygous mice." (PMID 41055965, 2025). "These genes are linked to systemic sclerosis and aneurysms, with NOTCH1 also being implicated in aortic valve disease." (PMID 38894765, 2024). "frequent affecting 1–2% of the general population; NOTCH1 variants are implicated in aortic valve diseases." (PMID 38187265, 2024). "NOTCH1 is associated with HLHS incidence primarily because of its pivotal role in Mendelian calcific aortic valve disease and compound heterozygous NOTCH1 mutations in HLHS subjects." (PMID 37894928, 2023). "Although NOTCH1 has been implicated in human aortic valve disease, Notch1 haploinsufficiency causes CAVD and ascending aortic aneurysms in mice, but not congenital aortic valve abnormalities." (PMID 37187784, 2023). "NOTCH1, encoding a member of the Notch family of proteins, is known to be associated with aortic valve disease." (PMID 32375772, 2020). "The Notch pathway is also important for aortic valve formation, and indeed mutations in the human Notch1 locus have been linked to aortic valve disease, most notably bicuspid aortic valve." (PMID 27020702, 2016). "For example, NOTCH-1 signalling, which is implicated in pathogenesis of aortic valve disease, is shown to play important roles in normal valvulogenesis of all the valves by regulating activity of various other genes and transcription factors." (PMID 25949830, 2015). "Two novel NOTCH1 nonsense mutations in two independent families were identified, both of which are located in the extracellular domain of the protein that has been associated with aortic valve disease." (PMID 27760138, 2016). "A recent study has suggested that NOTCH1 haploinsufficiency alters specific gene networks affecting valve development and osteogenic factors which in turn result in aortic valve disease." (PMID 27760138, 2016). "Loss of function mutations in NOTCH1 cause bicuspid aortic valve (BAV) and calcific aortic valve disease." (PMID 29552567, 2014). "In a large BAV/TAA cohort, SMAD6 variants were specifically enriched among patients with concurrent thoracic aortic aneurysms, while NOTCH1 and ACTA2 mutations were also documented in familial or heritable forms of aortic valve disease and aortic wall pathology." (PMID 41002609, 2025). "In addition, Nos3−/−; Notch1+/− mice develop aortic valve disease, indicating a genetic interaction between Nos3 and Notch1 in calcific progression." (PMID 34239905, 2021). "Interestingly, expression of Notch1, which is regulated by Nos3 signaling in aortic valve disease, is also reduced in Krox20−/− embryos." (PMID 31684048, 2019).
cholangiocarcinoma (20 papers, 2016 to 2025). A carcinoma that arises from the intrahepatic biliary tree (intrahepatic cholangiocarcinoma) or from the junction, or adjacent to the junction, of the right and left hepatic ducts (hilar cholangiocarcinoma). "In cholangiocarcinoma, Notch 1-3 expression was associated with lower histological differentiation and poorer survival of patients, and combining gemcitabine and GSI-IX prevented gemcitabine-induced enrichment of CSC-like population in in vitro models." (PMID 34680255, 2021). "Notch1 signaling is associated with proliferation, chemoresistance, metastasis, tumorigenesis and is overexpressed in many organ-specific cancers including liver and cholangiocarcinoma." (PMID 29152142, 2017). "Second, NO upregulates Notch-1 expression by activating transcription factors such as NF-κB, which is heightened in the inflammatory tumor microenvironment of cholangiocarcinoma." (PMID 40642105, 2025). "Notch-1 is hyper-expressed in cholangiocarcinoma cells, correlating with tumor growth and invasion, and its dependency on NO generation positions NO as a key regulator of BTC pathogenesis." (PMID 40642105, 2025). "In a separate study, genetic overexpression of NOTCH1 in the biliary epithelium accelerated KRASG12D-induced cholangiocarcinoma though its canonical effector, HES1." (PMID 37605966, 2023). "Early work concentrating on the role of NOTCH1 in cholangiocarcinoma demonstrated its role in the proliferation and migration of cholangiocarcinoma cells, and in mediating their chemosensitivity through the regulation of chemoefflux transporters." (PMID 37605966, 2023). "Given the reiterative use of NOTCH2 in mammalian bile duct biology, it is somewhat surprising that these early studies have identified NOTCH1 as essential for the formation of hepatocyte-derived cholangiocarcinoma." (PMID 37605966, 2023). "In nude mice, corilagin suppressed cholangiocarcinoma growth and downregulated the expression of Notch1 and mammalian target of rapamycin." (PMID 31546767, 2019). "The Notch1 signaling pathway was reported to enhance the expression of the cyclin E protein in cholangiocellular carcinomas." (PMID 31775892, 2019). "In summary, we show that xanthohumol significantly reduced cholangiocarcinoma growth through the Notch1/AKT signaling axis." (PMID 29152142, 2017). "In a different murine model in which the NOTCH1 ICD is expressed in the neonatal liver, cholangiocarcinoma initiation and growth promote the transcriptional regulation of Cyclin-E (CCNE1)." (PMID 37605966, 2023). "Livers tissue-specifically over-expressing the Notch1 intracellular domain (N1ICD Tg_Alb) had more tubular intrahepatic bile ducts and ultimately develop cholangiocarcinomas." (PMID 27358050, 2016). "On the other hand, Huntzicker and coauthors described that Notch1 inhibition altered the relative proportion of tumor types, reducing HCC-like tumors but dramatically increasing cholangiocarcinoma-like tumors." (PMID 27167202, 2016). "Similar epigenetic phenomena were described in human cholangiocarcinoma (CCA), in which Enhancer of zeste homolog 2 (EZH2)-mediated histone 3 trimethylation of lysine 27 (H3K27me3) in the same promoter lowered miR-34a levels and promoted Notch1 signalling." (PMID 37628760, 2023). "Interestingly, this study also noted cholangiocarcinoma (CCA) FFPE clinical specimens with FGFR2 RNA fusions without the 20 top actionable DNA NOTCH-1 mutations." (PMID 36213130, 2022). "A previous study using a mouse model of HCC and cholangiocellular carcinoma (CCC) induced by the overexpression of v-Akt and N-Ras oncogenes in hepatocytes reported the different effects of the blockade of Notch1, Notch2, and Notch3 signaling on the tumor progression." (PMID 35064244, 2022). "Furthermore, in cholangiocarcinoma, inhibition of EZH2 or DNA methylation repressed tumor cell growth in vitro and in vivo through the miR-34/Notch1 axis." (PMID 34680255, 2021).
cholangiocarcinoma (continued). "Downregulation of NOTCH1, among the targets, resulted in effective increase of sub-G1 cells, in line with the NOTCH signaling being a major player in cholangiocarcinoma progression with translational potential for cholangiocarcinoma." (PMID 28199974, 2017). "This was addressed in a hepatocyte-derived cholangiocarcinoma model, which was driven by the expression of oncogenic YAP (YAPS127A) and myrAKT and thus did not rely on the ectopic expression of the NOTCH1 ICD." (PMID 37605966, 2023).
diabetes (20 papers, 2013 to 2026). "This may suggest that, in addition to activation of the Notch-1 pathway, other factors associating with diabetes in the DN condition affected autophagy in podocytes." (PMID 30237561, 2018). "NaHS caused remission from the depression- and anxiety-like behaviours induced by type 1 diabetes mellitus by decreasing Notch1 signalling." (PMID 35732696, 2022). "Polydatin reduced MI/R cardiac damage during diabetes by activating the Notch1/Hes1-dependent Pten/Akt signaling pathway." (PMID 36235012, 2022). "Subsequently, Notch1 signaling blockage both in vitro as well as in vivo through either genetic or pharmacological methods was found to enhance wound healing in diabetes, via numerous mechanisms central for wound healing as cellular proliferation, migration, and angiogenesis." (PMID 34256844, 2021). "SAL may act to prevent β-cell dedifferentiation (and thus avert diabetes) by inhibiting the Notch1 pathway." (PMID 31440379, 2019). "Previous studies indicate that insulin resistance, as in diabetes, can increase Notch1 signaling." (PMID 27364742, 2016). "Previous studies have shown that Jag1 and Dll4 are secondary to increased hyperglycemia, activate the normative and non-normative Notch1 pathways, and destroy the endothelial adhesion connection in the retina in diabetes, which is consistent with our findings." (PMID 36533134, 2022). "At the same time, the IRF4 downstream pathways of Notch1 and p-AKT pathways are opened, indicating that diabetes is stimulated by various factors, and IRF4 may promote renal damage." (PMID 35518350, 2022). "Further adjustment for diabetes and hypertension did not substantially attenuate hazard ratios for ANGPT2, Spondin-1, TRAP5 or NOTCH1." (PMID 30557359, 2018).